AKT1 (AKT serine/threonine kinase 1)
Diseases named in the same sentence as AKT1 in open-access papers (continued):
Sharing a sentence is not in itself a finding about the gene and the disease.
cancer (continued). "AKT1 is relevant to longevity, and the dysregulation of AKT signaling leads to diseases for which there are major unmet medical needs, such as cancer, diabetes, and cardiovascular and neurological diseases." (PMID 33657282, 2021). "In cells, miR-185 suppresses cancer formation by inducing cell cycle arrest and apoptosis by targeting Ras Homolog-MTORC1 Binding (RHEB), RPTOR Independent Companion of MTOR Complex 2 (RICTOR), and AKT Serine/Threonine Kinase 1 (AKT1)." (PMID 34069740, 2021). "Given the role of AKT1 in tumorigenesis, this discovery may foreshadow a role of NMD in the cancer process." (PMID 34634811, 2021). "Additionally, glucose regulated protein 78 (GRP78) interacts with α2-macroglobulin to activate AKT1 via PDK1, as well as mTOR to enhance cancer cell proliferation and radiotherapy resistance in GBM." (PMID 32333246, 2020). "Transcriptome analysis of CKI-treated MDA-MB-231 cells revealed that PIK3CA, AKT1, and MAPK1 all affect cell migration, which may be related to the role of CKI in the treatment of cancer." (PMID 32020871, 2020). "Moreover, VEGFA, EGFR, CASP3, AKT1, and CCND1 were identified as hub genes in the antilung cancer of cinobufotalin injection." (PMID 32148531, 2020). "Moreover, using PPI networks, key cancer regulators such as MYC, VEGFA, AKT1, CDKN1A, RHOA, and PTEN are identified." (PMID 33281862, 2020). "Based on five relationship predictive methods provided by the UbiBrowser online tool, some potential targets were found and many of the substrates of these five E3 ubiquitin ligases, such as proteins in the JAK family, AKT1 and BRAF, are well-known oncoproteins in multiple cancer types." (PMID 33232269, 2020). "In the present study, amplification in MYC and AKT1 show a strong consistency with transcript levels and glycolysis-high tumors harbor increased MYC and AKT1 expression, suggesting that AKT1 and MYC activation contribute the glycolytic activation in some cancer type." (PMID 32635458, 2020). "AKT1 is part of the phosphatidylinositol 3-kinase (PI3K)/AKT pathway, a conserved intracellular signalling pathway that plays a central role in cellular quiescence, proliferation, cancer, placental development, and fetal growth." (PMID 32520951, 2020). "Notably, the MAPK1, AKT1 and PRKCA genes were enriched in a vast majority of vital cancer-related signaling pathways." (PMID 32665670, 2020). "On evaluating the expression in different tissue types such as normal, inflammation, hyperplasia, cancer adjacent tissues (CAT), and malignant tissues, it was found that the maximum expression of Akt1 and 2 was in malignant tumor types in comparison with normal tissues." (PMID 31252679, 2019). "Furthermore, the results show DawnRank missed more than one significant cancer driver genes including PTEN, PIK3CA and AKT1." (PMID 31888619, 2019). "That is the case of several cancer-cell lines that up-regulate CMA even in the presence of TORC2/AKT1 signaling pathway, which has a CMA inhibitory effect in normal cells." (PMID 31906065, 2019). "In detail, higher expression levels of AKT1 and AKT2 negatively influenced overall patients' survival, and in particular, AKT2 expression levels defined a group of luminal B BC patients with shorter cancer-specific survival." (PMID 31781306, 2019). "We compared protein and phospho-protein levels of AKT1 and AKT2 across different cancer lineages." (PMID 30012111, 2018). "VPA has also been shown to reduce the expression level of AKT1 by PCR array in cancer cells but its effect in ECs has not been reported." (PMID 30050438, 2018).
cancer (continued). "In terms of cancer, some studies have found that AKT2 may be the primary AKT for mediating PI3K-mediated metastatic processes, whereas others have concluded AKT1 to be as important." (PMID 28513565, 2017). "Although some growth regulators have been demonstrated to be good prognostic tools in many other common cancers, the connection between HBV CP mutations and AKT1 has not been carefully investigated by examining the prognostic value of HBV-associated HCC." (PMID 27779207, 2016). "Our results explored a novel mechanism relevant to activation of the AKT1 signaling pathway, and it may be an appropriate strategy to target SMYD3-mediated AKT1 methylation for the development of anti-cancer treatment." (PMID 27626683, 2016). "Consistently, both virgin and multiparous AKT1(E17K) mice develop mammary gland hyperplasia that do not progress to carcinoma." (PMID 27004402, 2016). "Consistently, transgenic mice expressing AKT1(E17K) driven by the MMTV promoter develop hyperplastic lesions that do not progress to carcinoma." (PMID 27004402, 2016). "Further, genome-wide gene expression analysis in EphA6 knock-down cells identified a panel of differentially regulated genes including PIK3IPA, AKT1, and EIF5A2, which could contribute to EphA6-regulated cancer progression." (PMID 26041887, 2015). "The AKT kinases (AKT1, AKT2, AKT3) represent the primary downstream end-point of the phosphoinositide 3-kinase (PI3K) pathway, regulating proliferation, survival, metabolism and invasion that are frequently activated in human cancer." (PMID 26053093, 2015). "To further confirm above notion in RY-2f mediated anti-cancer effects, we transfected A2780, HEY and OVCA433 cells with a plasmid containing constitutively active AKT1 (myr-AKT1) or control vector, respectively, and then determined the anti-proliferative effect of RY-2f on the transfected cells." (PMID 26325371, 2015). "A second point is made by our discovery of the synthetic lethal interaction between the alkylating agent bendamustine and the double AKT1/2 KO genetic background, which is unlikely to occur naturally in cancer cell lines or primary cells." (PMID 26700849, 2015). "When using SNVs only, most such genes were known cancer genes, such as U2AF1, IDH1, and DNMT3A in LAML (FLT3 SNVs cluster within five amino acids), AKT1 and KRAS in BRCA, BRAF and KRAS in COADREAD, IDH1 and PARG (poly (ADP-ribose) glycohydrolase) in GBM, and KRAS in UCEC." (PMID 25348067, 2014). "For example, in our study HRAS (P = 5.0 × 10-46), AKT1 (P = 9.5 × 10-26), PIK3CA (P = 5.5 × 10-5), B2M (P = 6.7 × 10-4), and KDM5C (P = 3.5 × 10-3) were predicted to be putative cancer genes using Fisher’s exact test and evidently designated as cancer driver genes according to the 20/20 rule." (PMID 25360158, 2014). "Inhibition of multiple components of the PI3K-AKT-mTOR axis in cancer cells is particularly attractive as mTOR exerts negative feedback regulation on AKT1 as demonstrated by the limited efficacy of rapamycin or its analogs." (PMID 23863691, 2013). "In addition, amplifications of AKT1 and AKT2, as well as of PIK3CA have been described in some cancers, but seem to play a subordinate role compared to the other described mechanisms." (PMID 24036443, 2013). "This is consistent with findings that AKT2 does not share complementary functions with AKT1 regarding cell invasiveness and survival in other forms of cancer." (PMID 20409325, 2010). "However, the effect of active Akt1 on migration and invasion might be cell line and/or cell-type specific, raising the possibility that downregulation of EF1α might have different effects on the migration of other cancer lines, depending on the relative concentration and activity of Akt isoforms." (PMID 19646290, 2009).
cancer (continued). "Regardless, our observation that Akt1 phosphorylates p27S10 in response to cellular stress has important implications for current efforts to understand how PI3K/Akt1 normally regulates p27, as well as how this process is disrupted in human cancers." (PMID 16780593, 2006). "In addition, miR-149 can target AKT1 to inhibit the proliferation of CRPC cells, which may be mediated by promoting apoptosis and inducing G1/S phase arrest in cancer cells." (PMID 40170845, 2025). "This dual mechanism—combining AKT1 pathway blockade with partial translation inhibition—may synergistically enhance antitumor efficacy, though synthetic lethality in PI3K-hyperactivated cancers requires further validation." (PMID 40806463, 2025). "Notably, we got interested in AKT1 and EGFR due to their role in cancer development." (PMID 40991529, 2025). "Identifying patients who may benefit from capivasertib after progression on first-line ET (i.e., those whose cancer has ≥1 PIK3CA, AKT1, and/or PTEN alterations), will provide an opportunity to achieve glycemic control, if needed, before initiating capivasertib." (PMID 41345397, 2025). "However, only AKT1, EGFR, BCL2, HSP90AA1, and PTGS2 exhibited strong binding affinities with pomegranate compounds, which are significantly declared in affected cells to enhance cancer progression." (PMID 40573291, 2025). "Interestingly, enforced expression of BMP4 resulted in a trend of increased AKT1 phosphorylation in both SMAD4-expressing and SMAD4-knockdown cells, consistent with previous reports of a similar effect by BMP2 in other cancers." (PMID 38689334, 2024). "Unlike AKT2, amplification of AKT1 is a rare occurrence in human cancer." (PMID 39614261, 2024). "We do not know the mechanism by which statins induce Akt1/Cav1 downregulation; nevertheless, statin-mediated attenuation of the Akt and mTOR signaling pathways has already been correlated with reduction of tumor burden in different cancers." (PMID 38473215, 2024). "tRF-21-VBY9PYKHD derived from tRNAGlyGCC could directly bind to Ser52 of hnRNP L, preventing the phosphorylation of hnRNP L by AKT2/AKT1, thereby inhibiting the formation of hnRNP L-DDX17 complex, ultimately inhibiting the invasion ability of cancer cells and promoting their apoptosis." (PMID 37953919, 2023). "We observed a significant correlation between the percentage of samples where a kinase is regulated in cancer and noncancer conditions (Pearson's r = 0.78, P‐value = 2.2e‐16), with AKT1 and the cell‐cycle kinases CDK1/2 and AURKB being highly regulated in both sets of conditions." (PMID 36688815, 2023). "Furthermore, several therapeutic agents inhibiting AKT1, such as perifosine and MK-2206 currently in phase III and phase II clinical studies, respectively, show improved prognosis in cancer patients through sensitizing cancer cells to different treatment modalities." (PMID 36230735, 2022). "Therefore, the prevention of angiogenesis through the inhibition of AKT1 and VEGFA could be an effective treatment strategy for many types of cancers." (PMID 35646655, 2022). "Additionally, AKT1, AKT2, and AKT3 isoforms are found to be overexpressed in several human cancers." (PMID 36192392, 2022). "Thus, we suggest that SNORA70E might regulate RAP1B and further regulates the expression of β‐catenin, PI3K, AKT1, mTOR, and MMP9 to exert cancer‐promoting effects." (PMID 36056690, 2022).
cancer (continued). "SEMA7A is known to signal through β1-integrin in immune cells, neurons, and cancer; β1-integrin also mediates MEC survival during development, in part, via phosphorylation and activation of downstream pro-survival signaling mediated by PI3-kinase and protein kinase B, or Akt1." (PMID 34561423, 2021). "In addition, it is reported that four downregulated genes of AKT1, CLECSF7, FGFR3, and LRP6 served as candidate genes and correlated with suppressing the biological processes in the cell cycle of cancer progression and the downstream signaling pathways of malignancy of melanocytic tumorigenesis." (PMID 33250779, 2020). "In addition, studies concentrating on somatic mutations in PIK3CA and AKT1 in pure IDP and later carcinomas lacked CNA data." (PMID 32195332, 2020). "Although a plethora of information from the cellular and pre-clinical studies have demonstrated the dual role of Akt1 activity in cancer, a correlation between Akt1 activity suppression and promotion metastasis has not been demonstrated in any type of human cancers." (PMID 31360736, 2019). "As FOXO1 connects to several of the cancer-associated genes adjacent to PBX3 (though not to PBX3 directly), the relative prominence of both FOXO1 and AKT1 might reflect a potential tumor-inhibiting effect in combination with PBX3 and its neighbors." (PMID 28957313, 2017). "Moreover, here we showed the involvement of AKT2, but not of AKT1, in the remodeling of the actin cytoskeleton, which is also relevant to cancer cell migration." (PMID 28287129, 2017). "In addition, post-translational modifications of AKT isoforms such as sumoylation or O-GlcNAcylation of AKT1, and ubiquitination of AKT1/2 are known to regulate AKT activation and may affect its function in cancer." (PMID 28082369, 2017). "The AKT2 and AKT3 (but not AKT1) isoforms are pathologically amplified in human cancers." (PMID 24967401, 2014). "However, genes lacking H3K27me3 in AKT1-transfected cells are realted to cell death whereas the genes without H3K9me2 are more enriched in cancer genes." (PMID 24564479, 2013). "In the absence of activated Akt1, whether and how cytoplasmic Skp2 is involved in the development of metastasis and cancer progression remains to be elucidated." (PMID 23300741, 2012). "Given the differential expression of AKT isoforms 1 and 2 and the low levels of expression of AKT3, the development of AKT 1/2 isoform selective inhibitors may be advantageous in cancer settings where the relative abundance of each isoform is specific to each cancer type." (PMID 36127435, 2022). "We also found AKT1-ARNTL positively correlated in HCT116 WT and SW480 control cells, whereas it was negatively correlated in ARNTL KO and PER2 KO in HCT116 and SW620 control cells, which might point to an alteration of clock regulation related to cancer progression." (PMID 35884519, 2022). "It was preliminarily predicted that NR could regulate the targets of CASP3, AKT1,ESR1,ACTB,MAPK3 and may modulate various pathways like estrogen signaling, thyroid hormone signaling pathway, prolactin signaling pathway, proteoglycan in cancer pathway, endocrine resistance pathway." (PMID 36401485, 2022). "Despite its close relationship with MCAK and functions on the mitotic spindle, KIF2A increases the migration rate of cancer cells via the AKT serine/threonine kinase 1 signaling, independent of its depolymerase activity, which could not be verified in MCAK overexpressing cells." (PMID 34830827, 2021).
cancer (continued). "Furthermore, western blot showed that inhibition of AKT1 reversed the effect of si-ATF3 to significantly increase Fas protein expression in tumor tissues, while to significantly decrease HLA-A, CCR5, FasL, HLA-E protein expression, which implied that the immune escape of cancer cells was diminished." (PMID 33794833, 2021). "This might explain the absent dichotomy of AKT1 in these cancer cells." (PMID 31752925, 2019). "On the basis of these results, Lys 14 of AKT1 is likely to be a key amino acid to determine AKT1 activity through the electrostatic attraction with Glu 17 and the interaction with phosphoinositides; SMYD3-mediated methylation of Lys 14 may trigger the constitutive activation of AKT1 in cancer cells." (PMID 27626683, 2016). "A previous study have shown that the full-length Par-4 interacts with Akt1 (cell survival kinase) through LZ domain to confer cancer cells resistant to apoptosis; however, SAC-domain lacking LZ domain could escape binding to Akt1 and can potentially kill cancer cells." (PMID 26500666, 2015). "Thus, cancers with N+C↓ AR expressed higher AKT1 levels, but this difference could not be detected on IHC due to abundant protein in all groups." (PMID 22114732, 2011). "The genes AKT Serine–Threonine Kinase 1 (AKT1) and SRC Proto-Oncogene, Non-Receptor Tyrosine Kinase (SRC), were up-regulated in the cancer compartment of PNI foci compared to non-PNI." (PMID 40075699, 2025). "Furthermore, expression of a constitutively active form of AKT1 by adenoviral vector prevents heart damage and protects mice from DOXO-induced cardiotoxicity, suggesting that the lack of insulin-mediated AKT1 activation during cancer progression could aggravate the cardiotoxicity induced by DOXO." (PMID 33547494, 2021). "TRIB2 preferentially binds to catalytically inactive, non-phosphorylated threonine 308 AKT1 in vitro and increases endogenous AKT phosphorylation at the hydrophobic motif (serine 473) in human cancer cells." (PMID 34070799, 2021). "Collectively, our results have shown the involvement of AKT2, but not AKT1 and AKT3, in cancer cell migration and invasion thereby acquiring the characteristics of cancer stem cell." (PMID 33227065, 2020). "These genes include very well-known cancer related oncogenes such as BRAF, ERBB2, AKT1 and PIK3CA with the genes which are not listed in the cancer gene census list of the COSMIC database." (PMID 32998690, 2020). "Lastly, they found that Akt1 and Akt3, but not Akt2, interact with DNA-PKcs in K-Ras mutant cells and stimulate DSB repair, thereby protecting cancer cell against IR." (PMID 33266502, 2020). "AKT comprises three isoforms (AKT1, AKT2, and AKT3), and the different isoforms are believed to mediate critical non-redundant or even opposing functions in cancer pathophysiology." (PMID 30012111, 2018). "CSF2 activates AKT1-, ERK1/2-, mTOR- but not JAK/STAT-dependent signaling cascades, which are active in many cancer stem cells." (PMID 28031533, 2017). "Although some crucial pathways (e.g., MAPK, Apoptosis, ERBB, JAK-STAT) were not top-ranked, core genes within these pathways (AKT1, EGFR, CASP3, TNF, SRC) showed high connectivity in the PPI network, reinforcing their relevance to the anti-cancer mechanisms of Siegesbeckiae Herba constituents." (PMID 41006588, 2025). "Therapeutic inhibition of the PI3K/AKT1 pathway has been proposed as a strategy to disrupt HR and sensitize cancer cells to PARP inhibition, and a nonrandomized trial of the pan-AKT inhibitor capivasertib suggested that AKT1E17K is a therapeutic target in metastatic solid tumors." (PMID 38175731, 2024). "However, reports regarding PFGFRA, HRAS, AKT1, FLT3, and NOTCH1 are lacking in the TCGA tonsil cancer data." (PMID 36979829, 2023). "Indeed, it interacts with and methylates several non-histone proteins (e.g., VEGFR1, HSP90, H2A.Z.1, MAP3K2, AKT1, ER, HER2), through which it activates specific pathways involved in the survival and proliferation of cancer cells." (PMID 35495117, 2022).